IL21R (interleukin 21 receptor)
Diseases named in the same sentence as IL21R in open-access papers (continued):
Sharing a sentence is not in itself a finding about the gene and the disease.
respiratory infection (3 papers, 2022 to 2025). "Here, we use the murine model of C. muridarum respiratory infection and IL-21R deficient mice to further identify a novel role of IL-21/IL-21R in neutrophilic inflammation." (PMID 35693111, 2022). "In the current study, transcriptome analysis showed that M1-related genes and a majority of M2-related genes were significantly downregulated in IL-21R−/− mice on day 7 post C. muridarum respiratory infection." (PMID 37628738, 2023). "In summary, our research highlights the critical role of IL-21/IL-21R signaling in promoting macrophage polarization towards M1 phenotypes and the pro-inflammatory effects of M1 during C. muridarum respiratory infection." (PMID 37628738, 2023). "Our results found the pathological effects of IL-21/IL-21R in C. muridarum respiratory infection through inducing excessive neutrophil infiltration, with IL-21R deficient mice exhibited less chemokines and proinflammatory cytokines responses." (PMID 35693111, 2022). "In this study, combined with the suggestions from the bioinformatic analysis, we used the animal models of C. muridarum respiratory infection of IL-21R−/− mice and the RAW264.7 macrophage cell lines to clarify the role of IL-21/IL-21R on Mφ in vivo and in vitro." (PMID 37628738, 2023). "It is emphasized that the IL-21/IL-21R signaling may play a role in recruiting mononuclear macrophages from the peripheral blood to infected sites during C. muridarum respiratory infection." (PMID 37628738, 2023). "Our results revealed that IL-21/IL-21R could promote the infiltration of pulmonary Mφ and induce polarization towards M1-type pro-inflammatory Mφ during C. muridarum respiratory infection." (PMID 37628738, 2023). "Therefore, it is particularly important to study whether IL-21/IL-21R aggravates chlamydia respiratory infection by regulating Mφ." (PMID 37628738, 2023). "However, the latent mechanism and effects of IL-21/IL-21R on innate immune response in C. muridarum respiratory infection remain unclear, thus warranting further investigation." (PMID 35693111, 2022).
atherosclerosis (2 papers, 2016 to 2023). A disease characterized by the build-up of fatty material and calcium deposition in the arterial wall resulting in partial or complete occlusion of the arterial lumen. "IL-21 and IL-21R inhibition has been frequently debated in the literature, where both higher and lower levels have been linked to atherosclerosis." (PMID 27095356, 2016). "While many immune pathways were enriched in the upregulated DEGs (e.g., CXCR5, IL21R, CCR7 and CD22) (A,C), pathways such as “lipid and atherosclerosis’ and “fluid shear stress and atherosclerosis” were enriched in the downregulated DEGs (such as NOS3, KLF2 and KLF4)." (PMID 37218991, 2023).
atopic dermatitis (2 papers, 2017 to 2024). "IL-21R in Extracellular Immunity, playing a pivotal role in atopic dermatitis by enhancing allergic immune responses with the promotion of migration of dendritic cells toward draining lymph nodes, displayed elevated expressions in various acute skin lesions." (PMID 38612783, 2024).
autoimmune thyroid disease (2 papers, 2013 to 2023). Inflammatory disease of the thyroid gland due to autoimmune responses leading to lymphocytic infiltration of the gland. "A previous study in the Chinese population reports an association of the genotypes TA and TT IL-21R rs3093301 with the development of autoimmune thyroid disease." (PMID 37107636, 2023).
autoimmune uveitis (2 papers, 2009 to 2019). An autoimmune form of uveitis (disease). "In summary, our study showed that increased IL-21 production and elevated IL-21R expression may be associated with the development of autoimmune uveitis in mice." (PMID 20057909, 2009).
chlamydia (2 papers, 2022 to 2023). "In C. muridarum-induced chlamydial respiratory infection mouse model, our previous study observed enhanced Th1 and Th17 immune responses, previously proved protective responses against chlamydial infection, in lungs of IL-21R deficient (IL-21R−/−) mice." (PMID 35693111, 2022). "In order to test the participation of interleukin-21 and its receptor (IL-21/IL-21R) in macrophages (Mφ) against chlamydial infection, we quantified IL-21R expression on the pulmonary Mφ by flow cytometry." (PMID 37628738, 2023). "Interleukin-21 and its receptors (IL-21/IL-21R) aggravate chlamydial lung infection, while macrophages (Mφ) are one of the main cells infected by chlamydia and the main source of inflammatory cytokines." (PMID 37628738, 2023). "IL-21/IL-21R signaling is involved in regulating diseases caused by various pathogens, not just chlamydia, and chlamydial respiratory infection is not solely associated with this signal." (PMID 37628738, 2023). "Thus, our study reveals the modulation and relevant mechanism of IL-21/IL-21R on neutrophilic inflammation, which expand the cognition of host immune mechanism against chlamydial infection." (PMID 35693111, 2022).
chronic lymphocytic leukemia (2 papers, 2015 to 2019). "IL-21 and IL-21R are emerging as promising targets for novel cytokine-based immunotherapies in many diseases, including SLE, primary immunodeficiency (PID), chronic lymphocytic leukemia (CLL), multiple myeloma (MM), and lymphoma." (PMID 31921177, 2019). "CpG oligodeoxynucleotides (ODNs) upregulate the interleukin-21 receptor (IL21R) and enhance IL-21-mediated cytotoxicity in chronic lymphocytic leukemia (CLL) B cells." (PMID 26158860, 2015).
cryptosporidiosis (2 papers, 2015 to 2024). Intestinal infection with organisms of the genus Cryptosporidium. "Notably, recent studies have uncovered mutations in the IL21R gene in patients experiencing chronic intestinal cryptosporidium infections, correlating with decreased function of peripheral lymphocytes." (PMID 25849970, 2015).
diffuse large B-cell lymphoma (2 papers, 2014 to 2017). "In the present study, the serum level of IL-21 and the expression of IL-21 on IL-21R with the pathogenesis of diffuse large B-cell lymphoma (DLBCL) was investigated." (PMID 24959288, 2014). "This led us to explore Grail and IL-21R expression patterns in CD8+ T cells from the peripheral blood of patients with either diffuse large B-cell lymphoma (DLBCL) or follicular lymphoma (FL)." (PMID 28798332, 2017). "In the present study, the effect of IL-21 and IL-21R on the pathogenesis of diffuse large B-cell lymphoma (DLBCL) was investigated." (PMID 24959288, 2014).
emphysema (2 papers, 2012 to 2017). "More importantly, a significantly positive correlation between the number of IL-21+Th17 and CD8+IL-21R+ T cells and emphysematous lesions was found in CS-exposed mice, which indicated the importance of IL-21+Th17 and CD8+IL-21R+ T cells in the development of emphysema." (PMID 23319833, 2012).
gastric cancer (2 papers, 2024 to 2025). A primary or metastatic malignant neoplasm involving the stomach. "In addition, IL21R functioned as an oncogenic factor in gastric cancer, and its high expression was associated with tumour size and lymphatic metastasis, which may represent a potential biomarker for gastric cancer." (PMID 38723244, 2024).
graft versus host disease (2 papers, 2019 to 2022). An immune system disorder that occurs after allogeneic hematopoietic stem cell transplant and is a reaction of donor immune cells against host tissues. "Transcripts for the pro-inflammatory cytokine Il12A, a mediator of graft versus host disease, Il18 and its receptor, Il21r, and Il1rl1 were lower in NP over FAT cells." (PMID 36406265, 2022). "On the other hand, amelioration of disease symptoms and improved health were observed after delivery of IL-21 neutralizing antibodies or IL-21R blockade in mice in multiple autoimmune and inflammatory disease models, including SLE, arthritis, graft-vs.-host disease (GVHD), and Crohn's Disease." (PMID 31921177, 2019).
Hepatic fibrosis (2 papers, 2017 to 2019). The presence of excessive fibrous connective tissue in the liver. "Notably, the numbers of IL21+ cells and IL21R+ cells were positively correlated with inflammation severity (r=0.45, P<0.05; r=0.43, P<0.05; respectively) and hepatic fibrosis stages (r=0.66, P<0.01; r=0.60, P<0.01; respectively) in PBC." (PMID 28425483, 2017).
Immunodeficiency (2 papers, 2015 to 2025). Failure of the immune system to protect the body adequately from infection, due to the absence or insufficiency of some component process or substance. "Nevertheless, immunodeficiency is one condition caused by loss of function mutations in the IL21 and IL21R genes." (PMID 40004558, 2025). "Such mutations in granulocyte colony-stimulating factor (G-CSF) receptor and interleukin-21 receptor (IL-21R) have been shown to cause severe congenital neutropenia (SCN) and a combined immunodeficiency syndrome, respectively." (PMID 26125015, 2015).
inflammatory skin disease (2 papers, 2024 to 2025). Inflammatory skin disorders covers a broad category that includes many conditions ranging in severity, from mild itching to grave medical health complications These disorders are common in people of all ages and races. "Other genes, such as IL-21R, GSDMC, CCR7, TLR9, HAS1/3, IL-17A, IL-22, and CXCL10, have been previously identified as genes associated with various inflammatory skin disorders." (PMID 38612783, 2024).
ischemia (2 papers, 2021 to 2022). A hypoperfusion of the BLOOD through an organ or tissue caused by a PATHOLOGIC CONSTRICTION or obstruction of its BLOOD VESSELS, or an absence of BLOOD CIRCULATION. "In summary, we have demonstrated that a novel angiogenic IL-21/IL-21R/miR-30b/STAT3 promotes endothelial cell survival under ischemia in PAD." (PMID 35008699, 2021).
melanoma (2 papers, 2021). A malignant, usually aggressive tumor composed of atypical, neoplastic melanocytes. "Prf1 and Gzmb levels in melanoma tumors from control and compound mutant mice as well as those treated with Cbx3-Il21r- or Il21r-deficient CD8+ effector T cells were low compared to Cbx3/HP1γ-deficient mice." (PMID 34721405, 2021). "Through protein expression scanning by the Human Protein Atlas, overexpression of FLI1, CD28, CD80, and IL21R was discovered in melanoma." (PMID 33971970, 2021). "Our data establish that LEF-1 and IL-21R are necessary for the optimal control of ovarian, melanoma and NBL tumor growth." (PMID 34721405, 2021). "Melanoma and NBL growth proceeded unchecked in tumor-bearing B6.SJL congenic mice treated with control, Il21r-/- or Cbx3-Il21r-deficient CD8+ effector T cells compared to animals receiving Cbx3/HP1γ-deficient CD8+ effector T cells." (PMID 34721405, 2021). "Our data underscore the fact that LEF-1 and IL-21R are requisite for the persistence of Cbx3/HP1γ-deficient CD8+ effector T cells in tumors with varied mutation loads that are ICB responsive (B16 melanoma) or non-responsive (ovarian and NBL)." (PMID 34721405, 2021).
myocarditis (2 papers, 2017 to 2023). Myocarditis is a condition that is characterized by inflammation of the heart muscle (myocardium). "Further, infected mice with transplanted IL-21R knockout CD8+ T cells have less CVB3-induced myocarditis than those transplanted with wild-type CD8+ T cells." (PMID 37669302, 2023). "In contrast to our study, Th17 responses were unaffected in IL-21R-/- mice with CIA, as well as in IL-21R-/- mice with experimental autoimmune encephalitis (EAE) and myocarditis (EAM)." (PMID 28158305, 2017).
Opportunistic infection (2 papers, 2018 to 2020). An infection that is caused by a pathogen that would generally not be able to cause an infection in a host with a normal immune system. "Biallelic loss-of-function mutations in IL21 receptor (IL21R) cause a severe syndrome characterized by respiratory tract infections, inflammatory complications and/or opportunistic infections, with elevated mortality in childhood." (PMID 32184784, 2020). "Additionally, activation of the IL-21/IL-21 receptor (IL-21R) pathway in T cells facilitates better control of human immunodeficiency virus (HIV) replication, while children with IL-21R deficiency are predisposed to opportunistic infections due to impaired cellular immunity." (PMID 29854291, 2018).
pancreatic tumor (2 papers, 2019 to 2020). "In summary, high numbers of intratumor IL-21+ infiltrates, aberrant expression of IL-21R, and its downstream target Blimp-1 in pancreatic tumor cells are associated with disease progression of PDAC." (PMID 31540511, 2019). "IL21R is expressed on pancreatic tumor cells and activates key signaling pathways." (PMID 31948053, 2020). "In vitro data with pancreatic tumor cells confirmed expression of IL-21R on pancreatic tumor lines." (PMID 31540511, 2019). "Therefore, three pancreatic tumor cell lines (AsPC-1, BxPC-3, and Panc-1) were tested for expression of IL-21R by western blotting and immunofluorescence staining." (PMID 31540511, 2019).
Respiratory tract infection (2 papers, 2020 to 2023). An infection of the upper or lower respiratory tract. "Next, we used IL-21R-deficient mice (IL-21R−/−) with Wild type (WT) mice as a control, to establish a Chlamydia muridarum (C. muridarum) respiratory tract infection model." (PMID 37628738, 2023). "We observed distinctly attenuated infiltration of Mφ in the lungs of IL-21R−/− mice during the early stage of C. muridarum respiratory tract infection in this study." (PMID 37628738, 2023). "We also found that IL-21/IL-21R may exacerbate neutrophilic inflammation by modulating the TLR/MyD88 signaling pathway during C. muridarum respiratory tract infection." (PMID 37628738, 2023).
Splenomegaly (2 papers, 2015 to 2024). Abnormal increased size of the spleen. "Despite increased anemia and splenomegaly, neither Il21-/- nor Il21r-/- mice had any other clinical signs." (PMID 25763578, 2015). "Indeed, adoptive transfer of B cells from IL-21R-deficient mice into WT mice during the HCC stage suppressed tumorigenesis, accompanied by splenomegaly and decreased lipid accumulation, but no change for the liver weight." (PMID 38720319, 2024).
thymic atrophy (2 papers, 2013 to 2023). "Since DEX modulates IL-21R expression on DP thymocytes, we next investigated the impact of in vivo rIL-21 administration on thymus function following induction of acute thymic atrophy." (PMID 24023776, 2013).
toxoplasmosis (2 papers, 2013 to 2017). A parasitic disease contracted by the ingestion or fetal transmission of toxoplasma gondii. "Therefore, in the next series of studies, we determined the role of IL-21 in CD8 T cell functionality during chronic Toxoplasmosis using IL-21R KO animals." (PMID 29163509, 2017).
vitiligo (2 papers, 2020 to 2024). Generalized well circumscribed patches of leukoderma that are generally distributed over symmetric body locations and is due to autoimmune destruction of melanocytes. "Highly significant changes in expression of CTLA4 and IL21R were found in growing feathers of vitiligo-expressing Smyth chickens (P < 0.0001)." (PMID 38720888, 2024). "A microarray study examining pools of cDNA from growing feathers of Smyth chickens collected before and at disease onset found evidence of both humoral (Ig-J chain, CXCL13) and cell-mediated (CCL19, GZMA, IL21R) immune activities prior to vitiligo onset." (PMID 38720888, 2024). "In addition to the expression of immunoregulatory genes prior to vitiligo onset in Smyth chickens, we observed a steady increase in IL21R expression, the receptor for IL-21." (PMID 38720888, 2024). "However, the IL21R was highly upregulated in lesional skin in the VKH and vitiligo dogs." (PMID 33384688, 2020).
anemia (1 paper, 2015). A reduction in the number of red blood cells, the amount of hemoglobin, and/or the volume of packed red blood cells. "The non-resolving P. chabaudi infection was accompanied by increased anemia in both Il21-/- and Il21r-/- mice from days 19–22 post-infection onwards." (PMID 25763578, 2015).
aneurysm (1 paper, 2025). Bulging or ballooning in an area of an artery secondary to arterial wall weakening. "In our study, we performed a gene set enrichment analysis (GSEA) to investigate the roles of ADIPOQ and IL21R in aneurysm pathophysiology, focusing on their involvement in immune-related pathways." (PMID 40313967, 2025). "In our study, a nomogram was constructed to predict the risk of aneurysm development using key biomarkers ADIPOQ and IL21R." (PMID 40313967, 2025). "IL21R showed positive correlations with activated CD4 T cells and activated B cells, highlighting its potential role in the immune landscape of aneurysms." (PMID 40313967, 2025).
autoimmune type 1 diabetes (1 paper, 2024). Autoimmune disease wherein the body's own immune system attacks and destroys the cells within the pancreas that produce insulin. "In an IL-21R-deficient non-obese diabetic (NOD) mouse model for autoimmune (type 1) diabetes, IL21 signaling was demonstrated to be indispensable for disease onset." (PMID 38720888, 2024).
babesiosis (1 paper, 2019). Babesiosis refers to a condition caused by microscopic parasites that infect the red blood cells. "The evidence supporting potential protective roles of the IL-21/IL-21R signaling axis during experimental murine babesiosis is limited." (PMID 31867283, 2019). "Collectively, the lack of experimental evidence demonstrating a direct and protective role played by the IL-21/IL-21R signaling axis precludes a definite conclusion as to how this signaling axis regulates host immunity during experimental babesiosis and may warrant further future studies." (PMID 31867283, 2019).